RBM38 (RNA binding motif protein 38)
Description:
Also acts as a mRNA splicing factor. Specifically regulates the expression of FGFR2-IIIb, an epithelial cell-specific isoform of FGFR2. Plays a role in myogenic differentiation. (Microbial infection) Essential factor for the splicing of the pre-mRNAs of human parvovirus B19 (B19V) and for the expression of B19V 11-kDa protein, which enhances viral replication.
Synonyms: RNPC1; HSRNASEB; SEB4D; seb4B; dJ800J21.2
Tractability: PROTAC: ubiquitination databases record sites on it; its protein half-life has been measured.
Gene: Protein-coding gene on chromosome 20 (57,391,396 to 57,409,333, forward strand). Ensembl gene ENSG00000132819.
Subcellular location: Cytoplasm, cytosol; Nucleus
Subcellular location (Human Protein Atlas): Cytosol; Nucleoplasm
Gene Ontology:
Molecular function: protein binding; RNA binding; mRNA 3'-UTR binding; mRNA binding; nucleic acid binding
Biological process: regulation of RNA splicing
Cellular component: cytosol; nucleoplasm; nucleus
Genetic constraint (gnomAD): Loss-of-function variants: 11 observed, 20.98 expected, observed/expected ratio (o/e) 0.52, 90% interval 0.33 to 0.87. The upper end of that interval is the gene's LOEUF score, 0.87, which puts it in group 3 of 6, group 1 being the genes least tolerant of losing a copy. Missense variants: 328 observed, 309.88 expected, observed/expected ratio (o/e) 1.06, 90% interval 0.97 to 1.16. Synonymous variants: 163 observed, 147.33 expected, observed/expected ratio (o/e) 1.11, 90% interval 0.97 to 1.26.
Homologues: Orthologues: macaque RBM38 (99% identical), pig RBM38 (97% identical), guinea pig RBM38 (96% identical), dog RBM38 (96% identical), mouse Rbm38 (95% identical), rat Rbm38 (94% identical), chimpanzee RBM38 (84% identical), tropical clawed frog rbm38 (69% identical), zebrafish rbm38 (61% identical), Caenorhabditis elegans sup-12 (47% identical). Paralogues in human: RBM24 (68% identical), RBMS1 (25% identical), RBMS2 (25% identical), RBMS3 (24% identical), PABPC1 (23% identical), SYNCRIP (23% identical), HNRNPR (22% identical), ELAVL2 (22% identical), PABPC3 (22% identical), PABPC4 (22% identical), PABPC1L (21% identical), ELAVL4 (21% identical), and 12 more.
Diseases named in the same sentence as RBM38 in open-access papers:
RBM38 is named in the same sentence as 44 diseases in open-access papers, as found by Europe PMC text mining. Sharing a sentence is not in itself a finding about the gene and the disease. The quoted sentences say what the papers report.
breast carcinoma (21 papers, 2013 to 2025). "PTEN expression was positively associated with the expression of RBM38 in breast cancer tissues and breast cancer cells." (PMID 29052531, 2017). "The results showed that the high expression of RBM38 was positively correlated with the low rate of distant metastasis and good prognosis in patients with breast cancer." (PMID 36059653, 2022). "Studies have shown that ectopic expression of RBM38 can inhibit the proliferation of breast cancer cells, while knockdown of RBM38 exhibits an opposite effect in vivo and in vitro." (PMID 36059653, 2022). "It is found that TGF-β induces a significant down-regulation of RBM38 in breast cancer, which is directly regulated by Snail, a transcription factor targeting at the E-box element of the RBM38 gene promoter region." (PMID 36059653, 2022). "The high expression of RBM38 is positively correlated with the low rate of distant metastasis and good prognosis in patients with breast cancer." (PMID 36059653, 2022). "In previous studies, it was confirmed that RBM38 plays a tumor suppressor role in cancer, such as gastric cancer, breast cancer." (PMID 35351042, 2022). "Conversely, c-Myc negatively regulates RBM38 expression by binding to the E-box in the promoter region of the RBM38 gene in breast cancer." (PMID 34804951, 2021). "For example, RBP RNA binding motif protein 38 (RBM38) inhibited cell proliferation through enhancing PTEN mRNA stability in breast cancer." (PMID 33381451, 2020). "Transforming growth factor-β (TGF-β) induces the expression of RNA-binding motif protein 38 (RBM38) in breast cancer, which promotes epithelial-to-mesenchymal transition by regulating the zonula occludens-1 transcript." (PMID 32194639, 2020). "In breast cancer, RNA-binding motif protein 38 (RBM38) participates in the TGF-β-induced EMT pathway and stabilizes the tumor suppressor gene PTEN transcript to enhance expression." (PMID 32653017, 2020). "In this study, we investigated a new post-transcription regulation mechanism of PTEN expression by RBM38 in breast cancer." (PMID 29052531, 2017). "This indicated that c-Myc negatively regulates RBM38 expression by binding to the E-box in the promoter region of the RBM38 gene in breast cancer cells." (PMID 28399911, 2017). "This provided a new insight into the mechanism of tumorigenesis and considering the importance of PTEN and RBM38 for the breast tumor progression and gene-targeted therapy for breast cancer." (PMID 29052531, 2017). "This indicates that c-Myc negatively regulates RBM38 expression in breast cancer cells by binding to the E-box motif in the promoter region of the RBM38 gene." (PMID 28399911, 2017). "Knockdown the expression of RBM38 is sufficient to induce the proliferation, aggressive behavior, and survival of breast cancer cells both in vivo and in vitro, while opposite effects were observed when RBM38 was overexpressed." (PMID 29052531, 2017). "In the present study, RBM38 overexpression decreased the levels of c-Myc protein and mRNA in breast cancer cells, whereas levels were increased by RBM38 knockdown." (PMID 28399911, 2017). "Recently, we have identified a potential tumor suppressor RBM38 (as known as RNPC1) in breast cancer, which also exhibited a tumor suppressor functions in colorectal cancer, acute myeloid leukemia, renal cell carcinoma and hepatocellular carcinoma." (PMID 29052531, 2017).
breast carcinoma (continued). "The colony formation assay showed that overexpression of RBM38 restrained the growth of the breast cancer cell BT474 and MDA-MB-453, which was consistent with our previous finding." (PMID 29052531, 2017). "Previously, RBM38 was found to be expressed at lower levels in breast cancer tissues compared to that in normal breast tissues, where it acts as a tumor suppressor." (PMID 28399911, 2017). "In our previous study, RNPC1, instead of RNPC1a, also called RBM38, was found expressed in breast cancer and had a potential function on playing a tumor-suppressor role." (PMID 25881544, 2015). "Additionally, RBM38 has been shown to participate in the progression of breast cancer, acute myeloid leukemia, colorectal cancer, and renal cell carcinoma, via transcriptionally regulating many downstream targets in different ways." (PMID 36059653, 2022). "Moreover, our previous study indicates that the RBM38 can suppress breast cancer metastasis through facilitating STARD13-related competing endogenous RNAs (ceRNA) network." (PMID 32653017, 2020). "This indicated that RBM38 negatively regulates c-Myc expression in breast cancer cells." (PMID 28399911, 2017). "In our previous study, ectopic expression of RBM38 could inhibit breast tumor cell proliferation, suppress tumor cell migration and invasion in breast cancer cells, acting as a tumor suppressor." (PMID 28399911, 2017). "Our previous study found that RBM38 acted as a tumor suppressor in breast cancer." (PMID 29052531, 2017). "Considering that both PTEN and RBM38 are tumor suppressor genes in breast cancer, we speculated that whether RBM38 functioned as a tumor suppressor by enhancing PTEN expression." (PMID 29052531, 2017). "In our previous study, RBM38 was identified as a tumor suppressor in breast cancer." (PMID 28399911, 2017). "Additionally, IHC analysis provided further evidence that RBM38 expression is negatively correlated with c-Myc expression in the breast cancer tissues." (PMID 28399911, 2017). "In addition, RBM38 has been identified as a tumor suppressor in breast cancer, and tends to form regulatory loops with its target genes." (PMID 28399911, 2017). "According to the results of RIP-seq (unpublished data), we found that PTEN mRNA might be bound by RBM38 directly in breast cancer." (PMID 29052531, 2017). "Notably, our previous study also identified novel targets of RBM38 in breast cancer." (PMID 36059653, 2022). "Therefore, we hypothesize PTEN expression can be regulated by a special mechanism in breast cancer: an RNA-binding protein, RBM38 can bind PTEN mRNA directly and affect its stability." (PMID 29052531, 2017). "For example, high expression of RNA-binding motif protein 38 (RBM38) represents longer overall survival in ovarian cancer, breast cancer, and glioma but implies poor prognosis in breast cancer." (PMID 37426488, 2023). "RBM38 acts as a tumor suppressor by reducing c-Myc and enhancing PTEN expression in breast cancer; Observations in most studies suggested that RBM38 promotes cancer." (PMID 35985767, 2022). "In a previous study, it was reported that RBM38 functions as a tumour suppressor, which can bind PTEN mRNA and maintain its stability, increasing mRNA levels of PTEN in breast cancer tissue." (PMID 34709758, 2021). "For example, the RNA binding motif protein 38 (RBM38), a tumor suppressor in breast cancer, was reported to be involved in the TGF-β signaling pathway and inhibit EMT by rescuing the expression of zonula occludens-1 to prevent cancer metastasis." (PMID 30819235, 2019).
breast carcinoma (continued). "Meanwhile, we also found that there was a positive correlation between the protein expression of RBM38 and PTEN in breast cancer tissues by using Western blotting." (PMID 29052531, 2017). "RBM38 can also increase the expression of phosphatase and tensin homolog gene on chromosome 10 (PTEN) by binding to the 3’-UTR of PTEN transcript, thereby inhibiting the cell proliferation of breast cancer." (PMID 34804951, 2021). "RNA-binding protein 38 (RBM38) was originally recognized as an oncogene and it was frequently found to be amplified in prostate, ovarian and colorectal cancer, chronic lymphocytic leukemia, colon carcinoma, esophageal cancer, dog lymphomas and breast cancer." (PMID 30662454, 2018). "As a member of the RNA recognition motif (RRM) family of RBPs, RNA-binding protein 38 (RBM38, also called RNPC1) has been shown to function as a tumor suppressor in breast cancer, acute myeloid leukemia, colorectal cancer, and correlates with improved survival in human ovarian cancer." (PMID 28399911, 2017). "Additionally, the RNA-binding motif protein 38 (RBM38), a pivotal mediator of TGF-β-induced EMT, positively regulates ZO-1 transcription via direct binding to AU/U-rich elements in its mRNA 3′-UTR in breast cancer." (PMID 36672179, 2023). "Moreover, overexpression of RBM38 increased PTEN mRNA and protein levels in breast cancer cells." (PMID 29052531, 2017).
colorectal cancer (8 papers, 2017 to 2023). A primary or metastatic malignant neoplasm that affects the colon or rectum. "In multiple types of cancer, e.g. breast- and colorectal cancer, Rbm38 expression is regulated, which indicates that Rbm38 function may represent a clinically relevant target." (PMID 28850611, 2017). "RBM38 is downregulated in CRC cell lines and inhibits colorectal cancer cell growth and stemness by competitively binding to PTEN." (PMID 36704343, 2022). "Fusobacterium nucleatum, a gram-negative anaerobic bacillus, is mainly associated with colorectal cancer patients positive for the CpG island methylator phenotype, although hypermethylation in genes such as MLH1, CDKN2A, MTSS1, RBM38, PKD1, PTPRT, and EYA4 has also been described." (PMID 37614819, 2023).
hepatocellular carcinoma (7 papers, 2014 to 2025). A malignant tumor that arises from hepatocytes. "Intriguingly, HOTAIR could promote migration and invasion of hepatocellular carcinoma cells by inhibiting RBM38 and activating the Wnt/β-catenin signaling pathway." (PMID 26172293, 2015).
non-small cell lung carcinoma (4 papers, 2020 to 2024). A group of at least three distinct histological types of lung cancer, including non-small cell squamous cell carcinoma, adenocarcinoma, and large cell carcinoma. "Overexpression of RBM38 inhibited non-small cell lung cancer cells proliferation, migration and invasion, and promoted cells apoptosis." (PMID 34804951, 2021).
colon carcinoma (3 papers, 2014 to 2018). "Hypoxia inducable factor 1α (Hif1α) is another stability target gene of Rbm38 in the breast- and colon carcinoma cell lines MCF7 and HCT116." (PMID 28850611, 2017). "Despite previous reports showing that the p21 mRNA transcript is stabilized by both Rbm24 and Rbm38 in breast- and colon carcinoma cell lines, we did not observe reduced p21 mRNA levels in Rbm38 -/- hearts." (PMID 28850611, 2017).
liver cancer (3 papers, 2017 to 2021). An epithelial or non-epithelial malignant neoplasm that arises from the liver. "We then conducted functional assays to investigate the molecular roles of RBM38 in inhibiting liver cancer cells aggressiveness in vitro and suppressing tumorigenicity in vivo." (PMID 30176896, 2018). "Ectopic expression of RBM38 could induce liver cancer cell apoptosis and senescence, inhibit proliferation and colony growth, and suppress migration and invasion in vitro." (PMID 34804951, 2021). "Furthermore, functional assays showed that ectopic expression of RBM38 could induce liver cancer cell apoptosis and senescence, inhibit proliferation and colony growth, and suppress migration and invasion in vitro." (PMID 30176896, 2018). "Furthermore, we conducted functional assays and found that ectopic expression of RBM38 could inhibit liver cancer cell proliferation and growth, induce apoptosis and senescence partly through inducing cell cycle arrest, and suppress migration and invasion in vitro." (PMID 30176896, 2018). "A study from Ding revealed that RBM38 is inhibited by HOTAIR in HCC, and up-regulation of RBM38 could suppress liver cancer cells migration and invasion in vitro." (PMID 30176896, 2018).
lymphoma (3 papers, 2017 to 2019). A malignant (clonal) proliferation of B- lymphocytes or T- lymphocytes which involves the lymph nodes, bone marrow and/or extranodal sites.
cervical cancer (2 papers, 2021 to 2025). A primary or metastatic malignant neoplasm involving the cervix. "Nonetheless, higher expression level of HENMT1, RBM38 and RNASEH2A showed a better overall survival of cervical cancer patients." (PMID 34863153, 2021). "The expression level of CTU1, RBM38, WDR43 varies with different pathology of cervical cancer." (PMID 34863153, 2021).
age (1 paper, 2026). A temporal measurement of the time period elapsed since an identifiable point in the life cycle of an organism. "For example, ZFHX4 (cg02298862) and RBM38 (cg18523477) are involved in DNA damage response, signal transduction, and DNA binding processes central to aging and age‐related diseases such as cancer." (PMID 41482678, 2026).
anemia (1 paper, 2017). A reduction in the number of red blood cells, the amount of hemoglobin, and/or the volume of packed red blood cells. "However, since Rbm38 -/- hearts are already hypertrophic at baseline, this trend can be secondary to the observed anemia in these mice." (PMID 28850611, 2017).
COVID-19 (1 paper, 2023). A disease caused by infection with severe acute respiratory syndrome coronavirus 2. "By excluding 4 genes, YBX3, RBM38, ANCA, and BLVRB, with opposite expression trends, we found that when compared to control samples, practically all of these genes showed persistently high expression in AMI and COVID-19." (PMID 38022594, 2023).
endometrial cancer (1 paper, 2021). Primary or metastatic malignant neoplasm involving the endometrium (mucous membrane that lines the endometrial cavity). "RBM38 overexpression attenuated the stemness of endometrial cancer spheres." (PMID 34804951, 2021).
Hodgkins lymphoma (1 paper, 2013). A heterogeneous group of malignant lymphoid neoplasms of B-cell origin characterized histologically by the presence of Hodgkin and Reed-Sternberg (HRS) cells in the vast majority of cases. "We also selected the non-Hodgkin lymphoma B cell line, RL-7, as a hematopoietic cell line amenable to siRNA for analysis of EPB41 splicing in response to RBM38 knockdown." (PMID 24250749, 2013).
lung carcinoma (1 paper, 2025). "TRIM17 is upregulated in cisplatin-resistant lung cancer tissues and cells and reduces cisplatin sensitivity of lung cancer cells by promoting ubiquitination and degradation of RBM38 protein." (PMID 41145484, 2025).